RESP18 (regulated endocrine specific protein 18)
Tractability: No criterion of Open Targets' tractability assessment is met for any kind of drug.
Gene: Protein-coding gene on chromosome 2 (219,327,407 to 219,335,552, reverse strand). Ensembl gene ENSG00000182698.
Gene Ontology:
Cellular component: endoplasmic reticulum
Genetic constraint (gnomAD): Loss-of-function variants: 23 observed, 24.78 expected, observed/expected ratio (o/e) 0.93, 90% interval 0.67 to 1.32. The upper end of that interval is the gene's LOEUF score, 1.32, which puts it in group 5 of 6, group 1 being the genes least tolerant of losing a copy. Missense variants: 265 observed, 237.6 expected, observed/expected ratio (o/e) 1.12, 90% interval 1.01 to 1.24. Synonymous variants: 102 observed, 98.3 expected, observed/expected ratio (o/e) 1.04, 90% interval 0.88 to 1.22.
Homologues: Orthologues: chimpanzee RESP18 (95% identical), macaque RESP18 (81% identical), rat Resp18 (39% identical), mouse Resp18 (38% identical).
Diseases named in the same sentence as RESP18 in open-access papers:
RESP18 is named in the same sentence as 3 diseases in open-access papers, as found by Europe PMC text mining. Sharing a sentence is not in itself a finding about the gene and the disease. The quoted sentences say what the papers report.
Parkinson disease (2 papers, 2022 to 2023). A progressive degenerative disorder of the central nervous system characterized by loss of dopamine producing neurons in the substantia nigra and the presence of Lewy bodies in the substantia nigra and locus coeruleus. "Resp18 deficiency may prevent the development of Parkinson’s disease by blocking MPTP-induced microglial activation and preserving dopamine neurons." (PMID 36110862, 2022). "The striatum and substantia nigra, two regions affected by Parkinson’s disease, abundantly express Resp18, a molecule that was recently shown to have an important role in Parkinson’s disease." (PMID 36110862, 2022). "Moreover, Resp18 knockdown mice have poorer locomotor activity in Parkinson’s disease." (PMID 37187956, 2023).
Hypertension (1 paper, 2023). The presence of chronic increased pressure in the systemic arterial system. "Resp18, as a candidate gene for hypertension, was validated by generating an SS-Resp18mutant rat on SS rat genetic background using a zinc-finger nuclease approach, targeting exon 3 of the Resp18 gene." (PMID 36672619, 2023). "Taken together, our findings suggest that the Resp18 gene is critical in maintaining an appropriate kidney function and blood pressure in an SS rat model for hypertension." (PMID 36672619, 2023).
neurodegenerative disease (1 paper, 2024). A disorder of the central nervous system characterized by gradual and progressive loss of neural tissue and neurologic function. "Other significantly downregulated genes were Resp18, Rtn1, Psap, Ubb, Aplp1, Cst3 and Itm2b, which are all associated with neurodegenerative diseases." (PMID 38017352, 2024). "Several genes involved in amyloid production were also found to be dysregulated by RH, including Aplp, Rtn1 and Itm2b, all of which have been associated with amyloid beta (Aβ) protein formation, and Resp18, Psap, Ubb and Cst3, all of which are associated with neurodegenerative diseases." (PMID 38017352, 2024).